GPC4 (glypican 4)
Diseases named in the same sentence as GPC4 in open-access papers (continued):
Sharing a sentence is not in itself a finding about the gene and the disease.
Alzheimer disease (3 papers, 2021 to 2025). A progressive, neurodegenerative disease characterized by loss of function and death of nerve cells in several areas of the brain leading to loss of cognitive function such as memory and language. "In human Alzheimer’s disease brain, microglial GPC4 expression surrounding Aβ plaques correlates with neuritic tau pathology, supporting a pathological link between amyloid, GPC4, and tau." (PMID 40883746, 2025). "Our study demonstrates that Aβ pathology drives the upregulation of microglial GPC4 in Alzheimer’s disease which, in conjunction with APOE, amplifies tau pathology." (PMID 40883746, 2025). "We next asked whether Alzheimer’s disease pathology can lead to GPC4 shedding from microglia thereby releasing soluble GPC4 into the extracellular space." (PMID 40883746, 2025). "Initially described as supporting functionality of synapses via glutamate receptors during CNS development, Glypican 4 (GPC-4) also plays a role in the context of dementia via tau hyperphosphorylation in Alzheimer’s disease, which is also a co-pathology in Parkinson’s disease dementia." (PMID 38424123, 2024).
Intellectual disability (3 papers, 2017 to 2020). "In addition, two cases of ASD and intellectual disability (ID) present point mutations in HARs within the GPC4 locus leading to decreased GPC4 expression." (PMID 29434536, 2018). "Interestingly, regions within both Gpc4 and RPTPδ have been identified as potential HARs, and two cases of ASD with intellectual disability (ID) were found that have point mutations in HARs of Gpc4 causing a significant decrease in Gpc4 expression." (PMID 29024665, 2017).
ovarian carcinoma (3 papers, 2014 to 2023). A malignant neoplasm originating from the surface ovarian epithelium. "GPC3 and GPC4 have been downregulated in oxaliplatin-resistant ovarian carcinoma cell line A2780/C10." (PMID 24804215, 2014).
rheumatoid arthritis (3 papers, 2009 to 2024). A chronic, systemic autoimmune disorder characterized by inflammation in the synovial membranes and articular surfaces. "GPC-4 is also associated with inflammation; it is upregulated on the surface of macrophages in rheumatoid arthritis." (PMID 39684750, 2024). "In a latest study of rheumatoid arthritis, GPC4 displays strong expression." (PMID 19134182, 2009).
breast tumor (2 papers, 2023 to 2025). "The effect of GPC4 downregulation was earlier demonstrated in relation to breast tumor progression, as well as in healthy tissues, to disruption of epithelial integrity and tight junction organization." (PMID 37239828, 2023). "Heparan sulfate proteoglycans (HSPGs) are abnormally expressed in BC tissues: GPC1 is overexpressed, while GPC3 and GCP5 show reduced expression, and GPC4 expression is downregulated in metastatic breast tumors compared with nonmetastatic breast tumors." (PMID 40443562, 2025). "Similarly, GPC4 expression is downregulated in metastatic breast tumors compared with nonmetastatic breast tumors." (PMID 40443562, 2025).
dementia (2 papers, 2024 to 2025). Loss of intellectual abilities interfering with an individual's social and occupational functions. "Our results suggest GPC-4 as a clinical biomarker for vascular risk stratification in order to identify PD patients with increased risk of developing dementia." (PMID 38424123, 2024). "Therefore, we hypothesize that serum GPC-4 could reflect the overall vascular risk in PD patients, which is per se an age-dependent risk factor for cognitive decline in different forms of dementia including PDD6,41." (PMID 38424123, 2024). "Future longitudinal clinical studies are warranted to validate the potential of GPC-4 for dementia tracing in neurodegenerative disorders." (PMID 38424123, 2024). "Alternatively, this association could reflect comorbid Aβ pathology, which is common in Parkinson’s disease with dementia and may similarly trigger microglial GPC4 release." (PMID 40883746, 2025). "The correlation of GPC-4 serum levels and MoCA score values in our study holds the potential to use serum GPC-4 as a molecular biomarker for vascular risk stratification in order to identify PD patients with increased risk of developing dementia, presumably of higher age." (PMID 38424123, 2024).
lung adenocarcinoma (2 papers, 2024). A carcinoma that arises from the lung and is characterized by the presence of malignant glandular epithelial cells. "In contrast, in lung adenocarcinoma patients, low levels of GPC4 were associated with poor prognoses." (PMID 38612755, 2024). "Conclusively, these results provide insights into potential mechanisms that explain the divergent proliferation outcomes of GPC4 upregulation between glioblastoma and lung adenocarcinoma." (PMID 38612755, 2024). "Finally, in order to better understand the contrasting effects of GPC4 upregulation between lung adenocarcinoma and glioblastoma observed in our in vitro experiments, we systematically studied genes with divergent gene expression profiles between TCGA-LUAD and TCGA-GBM subjects." (PMID 38612755, 2024).
Parkinson disease (2 papers, 2024 to 2025). A progressive degenerative disorder of the central nervous system characterized by loss of dopamine producing neurons in the substantia nigra and the presence of Lewy bodies in the substantia nigra and locus coeruleus. "Interestingly, a recent clinical study found that elevated GPC4 levels in the CSF and serum of Parkinson’s disease patients correlated with worse cognitive function, raising the possibility that soluble GPC4 may also be involved in synucleinopathies." (PMID 40883746, 2025). "However, clinical evidence of circulating GPC-4 in Parkinson’s disease (PD) is missing so far." (PMID 38424123, 2024).
schizophrenia (2 papers, 2018 to 2021). A major psychotic disorder characterized by abnormalities in the perception or expression of reality. "Finally, some members of the HSPG protein family, like GPC4, GPC5 and GPC6 have been linked to neurodevelopmental diseases such as autism, schizophrenia." (PMID 29434536, 2018).
Stroke (2 papers, 2023). Sudden impairment of blood flow to a part of the brain due to occlusion or rupture of an artery to the brain. "Pan-reactive astrocyte genes (Cxcl10 and Osmr), A1 neurotoxic genes (Amigo2, Ugt1a, Gpc4, H2-D1, and Iigp1), and A2 neuroprotective genes (Ptx3, Thbs2, and Tm4sf1) were all upregulated by NPD1 + RvD1 in the ipsilesional penumbra at 24 h after stroke." (PMID 37270727, 2023).
tauopathy (2 papers, 2024 to 2025). Neurodegenerative disorders involving deposition of abnormal tau protein isoforms (tau proteins) in neurons and glial cells in the brain. "Although GPC4 expression does not directly correlate with global tau pathology in AD or primary tauopathy patients, we asked whether GPC4 expression may locally correlate with neuritic plaques." (PMID 40883746, 2025). "Additionally, overexpression of GPC4 was found in ApoE4 carrier patient post-mortem brain, with ApoE4 surface trafficking via GPC4 gateways suggested to increase Tauopathy." (PMID 38546765, 2024).
amyloid cardiomyopathy (1 paper, 2026). "GPC-4 concentrations were determined in two prospective cohorts: patients with chronic heart failure with reduced ejection fraction (HFrEF), and with transthyretin amyloid cardiomyopathy (ATTR-CM)." (PMID 41944882, 2026).
amyloidosis (1 paper, 2025). A disorder characterized by the localized or diffuse accumulation of amyloid protein in various anatomic sites. "We stained brain sections with IBA1 and GPC4 antibodies as well as Amylo-Glo, a fluorescent dye that labels amyloid plaques." (PMID 40883746, 2025). "Glial GPC4 expression exacerbates motor deficits and reduces lifespan in a Drosophila amyloidosis model, implicating GPC4 in a toxic neurodegenerative program." (PMID 40883746, 2025). "After adjusting the GPC4-amyloid pathology correlation for tau pathology as a confounder by applying multiple linear regression, there was a significant relationship between GPC4 expression and amyloid pathology (r = 0.77; p = 0.0075), but not for tau pathology (r = 0.68; p = 0.2155)." (PMID 40883746, 2025). "We also note that neither the Drosophila nor the murine models of amyloidosis used in this study show elevated glial GPC4/Dlp expression, highlighting a limitation of these in vivo systems for modeling innate Aβ-induced microglial responses." (PMID 40883746, 2025). "Since microglial GPC4 expression is not observed in rodent models of amyloidosis, we employed Drosophila melanogaster to directly manipulate the glial expression of Dlp, the fly ortholog of human GPC4." (PMID 40883746, 2025).
Anxiety (1 paper, 2025). Intense feelings of nervousness, tension, or panic often arise in response to interpersonal stresses. "Juvenile GPC4 KO mice displayed hyperactivity in open-field tests, while adult GPC4 KO mice exhibited deficits in social novelty behaviours, with non-social behaviours such as working memory and anxiety unaffected." (PMID 41441843, 2025).
Arthritis (1 paper, 2008). Inflammation of a joint. "Selected HSPGs, such as syndecan-1, -2 and -3 and glypican-4, could play a part in the pathophysiology of arthritis, such as the migration and retention of leukocytes and angiogenesis in the chronically inflamed synovium." (PMID 17545191, 2008).
atherosclerosis (1 paper, 2023). A disease characterized by the build-up of fatty material and calcium deposition in the arterial wall resulting in partial or complete occlusion of the arterial lumen. "A relevant role of GPC4 in atherosclerosis could therefore help in understanding the observed gender differences in the prevalence of cardiovascular diseases." (PMID 37511353, 2023).
autosomal recessive omodysplasia (1 paper, 2018). Autosomal recessive form of omodysplasia. "However, the ability of glypican-4 to uncouple pluripotent stem cell differentiation from tumorigenic potential has been recorded, while the reduced expression or loss of function of glypican-6 has been described in retinoblastoma and autosomal-recessive omodysplasia." (PMID 29940912, 2018).
cholangiocarcinoma (1 paper, 2020). A carcinoma that arises from the intrahepatic biliary tree (intrahepatic cholangiocarcinoma) or from the junction, or adjacent to the junction, of the right and left hepatic ducts (hilar cholangiocarcinoma). "We selected 5 markers: CD44 and GPC4 were enriched in EVs from PDAC and cholangiocarcinoma organoids, while VGLUT2, CD14, and annexin A11 were enriched in EVs from PDAC organoids but not cholangiocarcinoma organoids." (PMID 32990680, 2020).
chronic heart failure (1 paper, 2026). "This study aimed to investigate the prognostic value of GPC-4 in chronic heart failure." (PMID 41944882, 2026). "GPC-4 carries strong prognostic value for all-cause death in chronic heart failure across various etiologies, but not for heart-failure specific outcomes." (PMID 41944882, 2026). "Circulating glypican-4 predicts prognosis in chronic heart failure, regardless of cause." (PMID 41944882, 2026).
chronic pancreatitis (1 paper, 2020). A chronic inflammatory process causing damage and fibrosis of the pancreatic parenchyma. "To challenge the potential of EV markers CD14, GPC4, ANXA11, and CD44v6 in detecting PDAC patients, we analyzed their levels in a larger cohort of patients with PDAC and underlying pancreatic diseases: chronic pancreatitis and intraductal papillary mucinous neoplasm (IPMN)." (PMID 32990680, 2020).
cognitive decline (1 paper, 2024). "This significant correlation between circulating GPC-4 levels in serum and the corresponding MoCA score indicates a potential role of GPC-4 in PD-associated cognitive decline, which appears even more prominent in PD patients of older age." (PMID 38424123, 2024). "We suggest that the potential of GPC-4 as a marker for vascular risk and/or cognitive dysfunction is not specific for PD, but may also be useful in other conditions associated with cognitive decline." (PMID 38424123, 2024). "Interestingly, GPC-4 levels were age-dependent, and multiple regression analysis revealed a significant association between GPC-4 serum levels and MoCA score, suggesting an involvement of GPC-4 in PD-associated cognitive decline." (PMID 38424123, 2024). "However, since in this study a relationship between GPC-4 and MoCA score could only be confirmed in serum but not in CSF, we assume that GPC-4 serum levels may be reflecting vascular pathology associated with cognitive decline." (PMID 38424123, 2024).
coronary artery disease (1 paper, 2023). "Recently, it was shown that increased serum GPC4 levels were highly and significantly associated with an increased risk of major cardiovascular events, vascular mortality, and all-cause mortality, supporting the role of GPC4 shedding in coronary artery disease." (PMID 37511353, 2023).
Cyclopia (1 paper, 2021). "However, ethanol concentrations greater than 1%, which did not cause cyclopia in wild-type siblings, resulted in cyclopia in gpc4 mutants." (PMID 34210294, 2021). "While 1% ethanol exposure altered the facial morphology of gpc4 mutants, it did not cause cyclopia." (PMID 34210294, 2021).
epilepsy (1 paper, 2022). A brain disorder characterized by episodes of abnormally increased neuronal discharge resulting in transient episodes of sensory or motor neurological dysfunction, or psychic dysfunction. "Of the glypican family, GPC3 and GPC4 have been implicated in the development and progression of epilepsy." (PMID 36289737, 2022). "GPC4 expression is elevated in neurons and astrocytes in the brains of epilepsy patients and in the neocortex and hippocampus of epileptic rats." (PMID 36289737, 2022).
gastric cancer (1 paper, 2022). A primary or metastatic malignant neoplasm involving the stomach. "Our data revealed that only GPC1, GPC4, and GPC5 were expressed in MKN74 gastric cancer cells." (PMID 36181793, 2022).
gestational diabetes mellitus (1 paper, 2021). "In conclusion, GPC-4 levels rose significantly during pregnancy, correlated negatively with fasting insulin and HOMA-IR but might not be related to gestational diabetes mellitus status." (PMID 34903856, 2021).
glioblastoma (1 paper, 2024). The most malignant astrocytic tumor (WHO grade IV). "Our survival analysis of GPC4 expression data in TCGA displayed an association between high levels of GPC4 expression and poor prognoses in glioblastoma patients." (PMID 38612755, 2024). "Additionally, a survival analysis of TCGA patient data substantiated these findings, revealing an association between elevated levels of GPC4 and a poor prognosis in glioblastoma, while indicating a favorable outcome in lung carcinoma patients." (PMID 38612755, 2024). "Opposite effects were obtained upon GPC4 overexpression, inducing proliferation of glioblastoma and suppressing proliferation of non-small cell lung adenocarcinoma cells." (PMID 38612755, 2024). "The results displayed that targeting GPC4 with CRISPR/Cas9 GPC4 attenuates the proliferation of glioblastoma cells and augments the proliferation of non-small cell lung adenocarcinoma cells in comparison with untreated cells and CRISPR controls." (PMID 38612755, 2024). "Further, the overexpression of GPC4 in GPC4-knocked-down glioblastoma cells restored the proliferation, indicating its mitogenic effect in this cancer type." (PMID 38612755, 2024). "In this study, we perform functional genomics assays in glioblastoma and non-small cell lung cancer in vitro models to understand how changes in GPC4 expression affect cancer proliferation, revealing divergent cancer type-dependent effects on proliferation." (PMID 38612755, 2024). "Our findings unravel the divergent effects of GPC4 on cancer progression and clinical outcome, particularly in glioblastoma and non-small cell lung cancer, and illuminates the pleiotropic effect of GPC4 on proto-oncogene singling pathways that govern mitogenic behavior." (PMID 38612755, 2024). "Next, the effect of CRISPR/Cas9 GPC4 on the proliferation of SNB-75 and SF-295 glioblastoma cells and HOP-92 non-small cell lung adenocarcinoma cells was investigated." (PMID 38612755, 2024). "The IPA analysis further unveiled enrichment of pathways associated with brain development, synaptogenesis, and axonal guidance, providing potential explanations for the impact of GPC4 in glioma and glioblastoma, which originate from neuronal and non-neuronal stem cells." (PMID 38612755, 2024).
heart failure (1 paper, 2026). Inability of the heart to pump blood at an adequate rate to meet tissue metabolic requirements. "Glypican-4 predicted all-cause death in heart failure with reduced ejection fraction and restrictive cardiomyopathy, but not heart failure-specific outcomes." (PMID 41944882, 2026).
ischemia (1 paper, 2026). A hypoperfusion of the BLOOD through an organ or tissue caused by a PATHOLOGIC CONSTRICTION or obstruction of its BLOOD VESSELS, or an absence of BLOOD CIRCULATION. "KEY MESSAGES : Glypican-4 rises with ischemia, inflammation, neurohumoral activity, and shear stress." (PMID 41944882, 2026). "Glypican-4 (GPC-4), an endothelial cell surface protein, is released into the circulation in the context of ischemia, inflammation, neurohumoral activity, and shear stress." (PMID 41944882, 2026).
kidney cancer (1 paper, 2024). Primary or metastatic malignant neoplasm involving the kidney. "Additionally, we detected a statistically significant association between higher levels of GPC4 and favorable outcomes in lung carcinomas and kidney cancers." (PMID 38612755, 2024). "Furthermore, elevated levels of GPC4 were shown to be associated with favorable outcomes in lung carcinomas and kidney cancers, indicating its multifaceted role in cancer." (PMID 38612755, 2024).
Krabbe disease (1 paper, 2024). A lysosomal disorder that affects the white matter of the central and peripheral nervous systems. "For example, glypican (GPC) proteins are differently affected in these models with GPC6 being decreased at the PM in a Krabbe disease model, while in GM2 gangliosidoses models, GPC4 is decreased and in GM3 synthase deficient cells, GPC4 accumulates at the PM." (PMID 39641585, 2024).
motor neuron degeneration (1 paper, 2017). "We hypothesized that if the production of non-membrane bound Glypican 4 and Glypican 6 via GPI-anchor cleavage was crucial to prevent degeneration, we should see diminished production of these proteins in mouse models that exhibit motor neuron degeneration." (PMID 28103900, 2017).
neuroblastoma (1 paper, 2025). Neuroblastoma (NB) is the most common solid, extracranial childhood tumor. "We co-applied tau-647 fibrils to SH-SY5Y cells, a human neuroblastoma cell line, along with GPC4 and APOE3, either alone or in combination, and measured internalization via flow cytometry 16 h later." (PMID 40883746, 2025).
peripheral artery disease (1 paper, 2022). "Recently, we showed that circulating GPC4 is associated with increased overall mortality risk in coronary angiography patients as well as in patients with peripheral artery disease." (PMID 36353562, 2022).
polycystic ovary syndrome (1 paper, 2021). A disorder that manifests as multiple cysts on the ovaries. "This study evaluated serum concentrations of galanin and glypican-4 in relation with the hormonal profile as well as metabolic and cardiovascular risk factors in patients with and without polycystic ovary syndrome (PCOS)." (PMID 33740336, 2021).
prostate carcinoma (1 paper, 2018). A carcinoma that arises from epithelial cells of the prostate gland. "Genes encoding FZD2-5, FZD8, VANGL1, ROR1, RYK, LGR4, LRP5 and 6, and GPC4 were highly expressed in at least three prostate cancer cell lines." (PMID 29717114, 2018).